COBLL1 (cordon-bleu WH2 repeat protein like 1)
Diseases named in the same sentence as COBLL1 in open-access papers (continued):
Sharing a sentence is not in itself a finding about the gene and the disease.
tumor (4 papers, 2009 to 2025). "Our study found that PACSIN2 plays a negative regulatory role against Cobll1 as a potential tumor suppressor in CML." (PMID 35352878, 2022). "Knockdown of ARHGDIA, COBLL1, and TM4SF1 resulted in 2- to 4-fold increased levels of apoptosis in normal cells (ARHGDIA only) and tumor cells (all three genes)." (PMID 21569526, 2011). "We provide evidence that ARHGDIA, COBLL1, and TM4SF1 are negative regulators of apoptosis in cultured tumor cells." (PMID 21569526, 2011). "We conducted a high-throughput RNA inhibition screen to knockdown gene expression levels of the four genes comprising the test (ARHGDIA, COBLL1, PKM2, TM4SF1) in both a human lung-derived normal and a tumor cell line using three different small inhibitory RNA molecules per gene." (PMID 21569526, 2011). "Knockdown of ARHGDIA, COBLL1, and TM4SF1 resulted in increased levels of apoptosis in normal cells (ARHGDIA only) and tumor cells (ARHGDIA, COBLL1, TM4SF1) relative to negative controls." (PMID 21569526, 2011).
infection (2 papers, 2016 to 2018). The state of being infected such as from the introduction of a foreign agent such as serum, vaccine, antigenic substance or organism. "In addition, a rare LCL that grew from an infection of primary B cells with EBNA3C KO virus showed that only EBNA3C-deficient LCLs expressed COBLL1." (PMID 26751214, 2016). "In order to determine whether binding of EBNA3C to RBPJ is necessary for the repression of the endogenous COBLL1 and ADAM28-ADAMDEC1 locus in the context of infection, a new EBV recombinant encoding the RBPJ binding mutant of EBNA3C (RBPJ BM EBNA3C) was constructed." (PMID 26751214, 2016). "Consistent with the results of the luciferase reporter assays and the ChIP studies, infection with the RBPJ BM EBNA3C virus was unable to repress ADAM28, ADAMDEC1 or COBLL1." (PMID 26751214, 2016). "All infections with EBNA3C competent viruses led to a remarkable 3–4 log fold reduction of COBLL1 mRNA over the same period of time, but this was not seen after infection with 3CKO virus–here the levels detected in primary B cells were maintained." (PMID 26751214, 2016). "Finally, in order to determine whether binding of EBNA3C to RBPJ was necessary for the repression of the endogenous COBLL1 and ADAM28-ADAMDEC1 locus, RNA samples taken every 5 days from the time of infection of primary B cells with the recombinant RBPJ BM EBNA3C virus were analysed." (PMID 26751214, 2016). "As expected, the EBNA3C knockout (3C KO) and EBNA3C RBPJ BM (3C RBPJ BM) viruses failed to regulate the COBLL1 mRNA level, whereas EBNA3C-competent viruses (WT and 3C Rev) resulted in a rapid reduction of COBLL1 gene expression over a period of 30 days after infection." (PMID 30135119, 2018).
metabolic disease (2 papers, 2022). A congenital disorder (due to inherited enzyme abnormality) or acquired (due to failure of a metabolically important organ) disorder resulting from an abnormal metabolic process. "However, in support of the COBLL1 role in metabolic disease, our study not only demonstrates fat-depot-specific COBLL1 mRNA expression, but also a significantly lower COBLL1 expression in sc AT of patients with T2D." (PMID 35955692, 2022). "GRB14/COBLL1 locus has been shown to be associated with body fat distribution (FD), but neither the causal gene nor its role in metabolic diseases has been elucidated." (PMID 35955692, 2022). "Therefore, sex-specific effects need to be carefully considered in further studies aimed at clarifying the role of COBLL1 and GRB14 in adverse body FD and associated metabolic disorders." (PMID 35955692, 2022). "Considering the strong correlation of GRB14/COBLL1 mRNA expression in AT and its potential function on lipid metabolism, we may need to consider the interaction of COBLL1 and GRB14 in adverse body FD and associated metabolic disorders in further studies." (PMID 35955692, 2022).
COBLL1 also shares sentences with these, for which no sentence is quoted: gastric cancer (2 papers); gestational diabetes (2); Lipedema (2); atherosclerosis (1); Impaired glucose tolerance (1); leukemia (1); liver disease (1); lymphoma (1); mesothelioma (1); neurodevelopmental disorder (1); preeclampsia (1).